RAC1 (Rac family small GTPase 1)
Diseases named in the same sentence as RAC1 in open-access papers (continued):
Sharing a sentence is not in itself a finding about the gene and the disease.
cardiac hypertrophy (continued). "Collectively, our results delineated that LAPTM5 ameliorates the development of pathological cardiac hypertrophy by interacting with Rac1 and then blocking the activation of the Rac1-dependent signaling cascade." (PMID 34692792, 2021). "At the molecular level, we identified that the beneficial effect of LAPTM5 on cardiac hypertrophy was largely dependent on the regulation of the Rac1-MEK-ERK1/2 signaling pathway." (PMID 34692792, 2021). "Taken together, these results demonstrate that LAPTM5 ameliorates the development of pathological cardiac hypertrophy by interacting with Rac1 and then blocking the activation of the Rac1-dependent signaling cascade." (PMID 34692792, 2021). "The cytoplasmic regulatory subunits of NADPH (p40phox, p47phox, p67phox and Rac1) are transferred to the plasma membrane for oxidase activation and ROS production in the process of pathological cardiac hypertrophy." (PMID 32209725, 2020). "Previous studies using isolated cardiomyocytes from transgenic mice over-expressing Rac1 in the myocardium showed the importance of Rac1 in the development of cardiac hypertrophy." (PMID 22936985, 2012). "To examine the role of Rac1 S-palmitoylation in a model of pathologic cardiac hypertrophy and failure driven by hypertrophic signaling in cardiomyocytes and independent of changes in blood pressure, we crossed Rac1cKI mice with transgenic mice overexpressing AT1R in cardiomyocytes (TgAT1R mice)." (PMID 40924486, 2025). "For example, targeting of ASK1 with an ASK1 inhibitor, selonsertib, which prevented AngII-induced cardiac hypertrophy and fibrosis in mice, or activation of PAK1 are potentially indirect means of effectively targeting Rac1-regulated pathogenic signaling in cardiomyocytes." (PMID 41333012, 2025). "Plenty of evidence has demonstrated that a number of GEFs can be activated by hypertrophic stimuli (PE, Ang II, endothelin-1, Stretch and others) through GPCRs, receptor tyrosine kinases, and other membrane receptors to activate Rac1 and eventually lead to cardiac hypertrophy." (PMID 37524688, 2023). "In our mechanistic exploration, we found that DEF6 could directly interacted with Rac1 and enhance activities of Rac1 through increasing the binding ability of Rac1 with GTP in pathological cardiac hypertrophy." (PMID 37524688, 2023). "Our study substantiates that DEF6 acts as a deleterious regulator of cardiac hypertrophy by activating the Rac1 and MEK1/2-ERK1/2 signaling pathways, and suggests that DEF6 may be a potential treatment target for heart failure." (PMID 37524688, 2023). "Numerous studies have verified the crucial role of Rac1 in the pathogenesis of cardiac hypertrophy." (PMID 37524688, 2023). "Therefore, inhibition of Rac1 signaling by enhanced RGS3L expression is a potential cardioprotective therapeutic strategy in cardiac hypertrophy, fibrosis, arrhythmias, and heart failure." (PMID 35230541, 2022). "RAC1 is necessary for the development of myocardial hypertrophy." (PMID 33560596, 2021). "In conclusion, SCO, an antioxidant, may attenuate Ang II‐induced myocardial hypertrophy by suppressing of RAC1 mediated oxidative stress." (PMID 33560596, 2021). "In conclusion, we have demonstrated a novel function of SCO in the protective effect of Ang II‐induced myocardial hypertrophy both in vitro and in vivo, and the effect may be mediated by inhibition of RAC1‐dependent oxidative stress." (PMID 33560596, 2021). "Indeed, expression of dominant-negative Rac1 has been shown to impede ROS production in cardiomyocytes following mechanical stress-induced cardiac hypertrophy." (PMID 27442895, 2017). "Since Rac1 is essential for Nox function and cardiac hypertrophy resulted to some extent by oxidative stress, probably the statins could reduce cardiac hypertrophy by antioxidant pathway." (PMID 27774507, 2016). "Moreover, inhibition of Rac1 protein in the course of statin therapy accounted for a decreased development of cardiac hypertrophy." (PMID 24128347, 2013).
cardiac hypertrophy (continued). "Also, over-expression of a constitutively active form of human Rac1 in the hearts of transgenic mice resulted in cardiac hypertrophy and cardiac dilation." (PMID 22936985, 2012). "However, genetic deletion of Rac1 in the heart is unable to rescue cardiac maladaptation observed with zDHHC3 overexpression, and Zdhhc3 heart-specific null mice still show robust cardiac hypertrophy over 8 weeks of TAC stimulation or 2 weeks of Ang-II infusion." (PMID 37926281, 2023). "Indeed, while alterations in the Cdc42 and Rac1 signaling of cardiomyocytes affect the development of cardiac hypertrophy and heart failure, these Rho GTPases can have important roles in other cell types of crucial importance in the heart, including cardiofibroblasts and endothelial cells." (PMID 36077014, 2022). "Furthermore, LAPTM5 could play an important protective role in pathological myocardial hypertrophy through the Rac1-MEK-ERK1/2 pathway." (PMID 36046710, 2022). "Therefore, SCO may block Ang II‐induced cardiac hypertrophy by inhibiting RAC1‐mediated oxidative stress." (PMID 33560596, 2021). "Importantly, cardiomyocyte-specific Rac1 deletion in a transgenic mouse model was associated with reduced NADPH activation and myocardial oxidative stress, which correlated with decreased cardiac hypertrophy despite being subjected to angiotensin II-induced hypertensive stress." (PMID 27442895, 2017). "Modification of Rac1 by protein palmitoylation restrains hyeractive protein kinase A (PKA) activity and pathological cardiac hypertrophy and adverse remodeling in response to stress." (PMID 40924486, 2025). "In a rabbit model of Myh7-Q403-driven cardiac hypertrophy, treatment with simvastatin reduced ERK phosphorylation and did not affect Rac1 GTP-loading, however it did appear to mildly reduce Rac1 membrane localization." (PMID 41333012, 2025). "In conclusion, activation of Rac1 and MEK-ERK signaling cascades are some of the mechanisms by which DEF6 accelerates the development of pathological cardiac hypertrophy." (PMID 37524688, 2023). "In terms of mechanism, RAC1 and the MEK-ERK signaling cascade activation largely contributed to DEF6’s deleterious role in cardiac hypertrophy." (PMID 37524688, 2023). "The further rescue experiments using Rac1 inhibitor NSC23766 treatment and AdRac1(G12V) infection verified the requirement of Rac1 and MEK1/2-ERK1/2 activation for DEF6-mediated pathological cardiac hypertrophy." (PMID 37524688, 2023). "Notably, induction of Rac1 S-palmitoylation in DTgZdhhc3 hearts occurred within 2 weeks of transgene expression, prior to the development of cardiac hypertrophy and heart failure, suggesting that modification of Rac1 may be a proximal mechanism underlying zDHHC3 activity–induced cardiac pathology." (PMID 37926281, 2023). "In the end, western blot and rescue experiments using Rac1 inhibitor NSC23766 and the constitutively active mutant Rac1(G12V) verified the requirement of Rac1 and MEK1/2-ERK1/2 activation for DEF6-mediated pathological cardiac hypertrophy." (PMID 37524688, 2023). "In cardiomyocytes and cardiac fibroblasts, Ang II activated Rac1 (increasing expression of RAC1-GTP), as well as NOX2 and NOX4 involvement in cardiac hypertrophy and fibrosis has been indicated." (PMID 36359731, 2022). "Mechanistically, LAPTM5 directly bound to Rac1 and further inhibited MEK-ERK1/2 signaling, which ultimately regulated the development of cardiac hypertrophy." (PMID 34692792, 2021). "In Ang II‐stimulated mice, cardiomyocyte‐specific knockout of RAC1 resulted in decreased NADPH oxidase activity, cardiac hypertrophy and myocardial oxidative stress." (PMID 33560596, 2021). "Treatment of Myh7-Q403 rabbits with atorvastatin reduced cardiac hypertrophy and fibrosis, however the effect of atorvastatin was reported to not affect Rac1 activity or membrane localization in these animals, although these data were not shown." (PMID 41333012, 2025).
cardiac hypertrophy (continued). "In wild-type mice, statins reduced Rac1 expression, myocardial hypertrophy, and fibrosis, but not in mice lacking SmgGDS." (PMID 38732177, 2024). "Rac1 is also an essential mediator of reactive oxygen species generation in the heart through regulation of the NADPH oxidase-2 (Nox2) complex and is required for cardiac hypertrophy and oxidative stress in response to angiotensin II." (PMID 37926281, 2023). "Additionally, activation Rac1-a significant regulator of NOX activity in adult hearts, is required for Ang II-induced cardiac hypertrophy." (PMID 36359731, 2022). "In addition, Rac-1/NADPH oxidase-derived oxidative stress is involved in the pathogenesis of MetS and participates in the production of cardiac hypertrophy." (PMID 28191276, 2017). "However, cardiomyocyte-specific Rac1 knockin mice (Rac1cKI/cKI; Myh6-Cre) exhibited significantly exacerbated cardiac hypertrophy in response to AngII, indicating hypersensitivity to AngII-induced cardiac hypertrophy in the absence of Rac1 S-palmitoylation." (PMID 40924486, 2025). "Global deletion of dedicator of cytokinesis 10 (DOCK10), a Rac GEF, resulted in more severe cardiac hypertrophy following AngII infusion and a greater reduction in p38 and JNK activation following acute PE treatment, however no direct effects on Rac1 activation were demonstrated." (PMID 41333012, 2025).
osteosarcoma (29 papers, 2005 to 2025). A usually aggressive malignant bone-forming mesenchymal neoplasm, predominantly affecting adolescents and young adults. "We also confirmed that miR-224 mimics/miR-224 inhibitors can reverse the up-regulation/down-regulation of Rac1 expression caused by circSRSF4/circSRSF4 si-circ in osteosarcoma cells." (PMID 35682879, 2022). "HACE1-deficient osteosarcoma cells had elevated levels of active RAC1, which was associated with increased ROS levels." (PMID 30622235, 2019). "Ectopic expression of HACE1 markedly inhibited anchorage-independent growth and cell motility of HACE1 osteosarcoma cell lines, and was associated with reduced RAC1 activation and decreased reactive oxygen species (ROS)." (PMID 30622235, 2019). "In contrast, when osteosarcoma cells express a constitutively activated Rac1 protein, the downregulation of MAP1B causes a strong increase in the percentage of fast comets, analogous to our observations in large growth cones." (PMID 30065631, 2018). "Other modulators of Rac1 have also been implicated in osteosarcoma metastasis." (PMID 27966608, 2016). "PAK7, a member of the p21-activated kinase family, promotes cell invasion in gastric and osteosarcoma contexts via the Rac1/Cdc42 pathway." (PMID 41153973, 2025). "According to previous studies, Rac1 participates in the tumor metastasis-related transduction pathways and is closely related to the occurrence and development of osteosarcoma." (PMID 35682879, 2022). "There is a possibility that there is a network regulation relationship between circSRSF4, miR-224, and Rac1 in osteosarcoma." (PMID 35682879, 2022). "Secondly, we observed that Rac1 promotes the proliferation, growth, migration, and invasion of osteosarcoma cells." (PMID 35682879, 2022). "In summary, our research revealed the key role of the circSRSF4/miR-224/Rac1 axis in the development of osteosarcoma." (PMID 35682879, 2022). "The results of the qRT-PCR and Western blot analysis show that the expression of Rac1 mRNA and protein in osteosarcoma tissues were significantly higher than those in the adjacent tissues (N: normal adjacent normal tissues, T: tumor osteosarcoma tissue)." (PMID 35682879, 2022). "To summarize, these data indicate that circSRSF4 acted as a sponge for miR-224, thereby regulating the expression of Rac1 in osteosarcoma." (PMID 35682879, 2022). "Further in vitro and in vivo mechanism studies showed that circSRSF4 can down-regulate the expression of Rac1 through binding with miR-224 competitively, which eventually leads to the weakening of proliferation, invasion, and migration of osteosarcoma cells." (PMID 35682879, 2022). "A mechanistic study showed that circSRSF4 can be used as an miR-224 sponge to up-regulate the expression of Rac1, thereby promoting the development of osteosarcoma." (PMID 35682879, 2022). "Together, these support a model whereby HACE1 downregulation results in enhanced RAC1 activation and ROS accumulation, contributing to osteosarcoma progression." (PMID 30622235, 2019). "HACE1 overexpression significantly downregulated both active RAC1 and ROS levels, pointing to a potential link between HACE1 loss and ROS regulation in osteosarcoma." (PMID 30622235, 2019). "RAC1 expression is upregulated in the osteosarcoma cell lines and tissues, and its ectopic expression promotes the proliferation, migration, and invasion of MG-63 cells." (PMID 29651441, 2018). "ERBB4 leads to activation of PI3K-AKT, focal adhesion kinase (FAK) and the RAC1 GTPase, a mediator of cell migration and invasion, pathways that are already been described in osteosarcoma pathogenesis." (PMID 29113313, 2017). "We evaluated the activations of RhoA, Rac1 and Cdc42 in osteosarcoma MG-63 and U2OS cells with small G-protein activation assay." (PMID 28289332, 2017).
osteosarcoma (continued). "Using C28/I2 chondrocyte cells, we have shown that silencing Rac1 by siRNA reduces the activation of p38 MAPK, which is reported to be linked to the upregulation of MMP13 by inflammatory cytokines and in osteosarcomas." (PMID 24180431, 2013). "To identify downstream targets of Rac1 that promote pioneer MTs, we sought to utilize an RNAi screening approach with U2-OS osteosarcoma cells due to their human origin and amenability to transfection." (PMID 22848487, 2012). "Our results show that Rac1 mRNA and protein were highly expressed in osteosarcoma tumor tissues and cells, suggesting that Rac1 is closely related to the occurrence and malignant biological characteristics of osteosarcoma." (PMID 35682879, 2022). "Therefore, our results confirm that circSRSF4 plays a key role in the development and metastasis of osteosarcoma by regulating the function of Rac1, and may become a new target and strategy for clinical prevention and treatment of osteosarcoma." (PMID 35682879, 2022). "In osteosarcoma cells, CaMKIIα increases the phosphorylation of T-lymphoma and metastasis gene 1 (Tiam1) and its membrane localization, and then activates ras-related C3 botulinum toxin substrate 1(Rac1), inhibits the expression of p21CIP/KIP and leads to a cell cycle progression." (PMID 25961153, 2015). "In mouse embryonic fibroblasts and human osteosarcoma cells, the GTPase activating protein RacGAP1 is also found in the β1-integrin:Rac1:IQGAP1 complex, where it inactivates Rac1." (PMID 37071417, 2023). "miR-124 inhibited cell growth and invasion in osteosarcoma cells by targeting ROR2, SPHK1, Rac1 and B7-H3." (PMID 29113367, 2017). "To summarize, we have identified the Rac1- and Cdc42-specific GAP, cdGAP as a key mediator of FA based mechanosensing of the ECM and as an important regulator of durotaxis in U2OS osteosarcoma cells." (PMID 24632816, 2014). "MALAT1 promotes the progression of osteosarcoma via upregulation of RhoA, ROCK and Rac1." (PMID 31248165, 2019). "Recent literature data suggested that in osteosarcoma the panel of expression of PLC isoforms varies in a complex and unclear manner and is related to ezrin, probably networking with Ras GTPases, such as RhoA and Rac1." (PMID 27026853, 2016). "In order to verify whether circSRSF4 promoted the proliferation, invasion, and migration of osteosarcoma through the circSRSF4/miR-224/Rac1 axis, we co-transfected the Rac1 overexpression plasmid with the 3’UTR region and circSRSF4 siRNA into osteosarcoma cells for a rescue experiment." (PMID 35682879, 2022). "However, analysis of osteosarcoma cells overexpressing the ARHGAP25 G218R‐mutant, combined with structural modeling, confirmed that the mutant protein had decreased GAP‐activity against Rac1, resulting in elevated Rac1 activity, increased cell spreading, and membrane ruffling." (PMID 34258505, 2021).